RB1 (RB transcriptional corepressor 1)
Diseases named in the same sentence as RB1 in open-access papers (continued):
Sharing a sentence is not in itself a finding about the gene and the disease.
tumor (continued). "Therefore, among the molecular genetic prognostic factors, expressions of RB1 and p16INK4 in the tumor cells were the most strongly predictive of adverse outcomes in stage I and II nonsquamous NSCLC." (PMID 22619677, 2012). "The RB116 cell line was established from this tumor and analyzed for expression of RB1." (PMID 23233783, 2012). "Next, to examine whether CCND1 and CDKN2A could be utilized as an RB1 classifier in vivo, the RB1 status was determined in xenograft tumor samples." (PMID 21447152, 2011). "However, melanocytes were immortalized in culture with constitutive β-catenin activation through downregulation of p16INK4a, a protein which regulates RB1 and thus has an important tumor suppressor function." (PMID 24281103, 2010). "In this graphical representation from data, the RB1 tumor suppressor, discussed in greater detail below, is detected in a peak of similarly merged regions that refines the boundaries of an ROI from those spanning ∼3 mb of sequence and 20 genes to those ∼237 kb spanning just two genes." (PMID 18784837, 2008). "These tumours also concurrently showed low expression of RB1 mRNA." (PMID 18782450, 2008). "The left most group contained 29 of 40 (72.5%) of the RB1 LOH-normal tumours." (PMID 18782450, 2008). "Interestingly, E2F1, E2F3 and E2F5 were present on this supervised gene list and highly expressed in tumours with RB1 LOH." (PMID 18782450, 2008). "Moreover a radiation – induced chromosome instability of single normal RB1 copy seems to be involved in tumor development." (PMID 19077296, 2008). "In total, 26 tumours showed RB1 LOH for at least one marker (26 of 67, 38.8%)." (PMID 18782450, 2008). "Subsequently, loss of heterozygosity (LOH) has been observed in primary tumours, but does not necessarily correlate with low RB1 protein expression as assessed by immunohistochemistry." (PMID 18782450, 2008). "Dyer and Bremner have proposed either a "progenitor cell model" or a "transition cell model" in which epigenetic and/or genetic differences in individual RB cells could lead to tumor formation upon inactivation of the RB1 tumor suppressor gene." (PMID 17615543, 2007). "The finding of protective RB1 alleles was unexpected, as deletions or inactivating mutations of the gene observed in tumours generally lead to an absence of negative control of the protein on the cell proliferation." (PMID 16685266, 2006). "No case showed mobility shifts by PCR-SSCP analysis of the RB1 promoter region and, thus no inactivating mutations were found in any tumour examined." (PMID 12556968, 2003). "Although the low number of samples available for analysis makes it difficult to draw firm conclusions, the data suggest that epigenetic inactivation of RB1 gene in parallel to methylation is a frequent mechanism that contributes to tumour development or progression in these neoplasms." (PMID 12556968, 2003). "LOH was found in 65 tumours, which all showed simultaneously loss of BRCA2 and RB1." (PMID 7577475, 1995).
tumor (continued). "The in situ hybridisations revealed mutually exclusive topographic distribution of myc and glial fibrillary acidic protein (GFAP) mRNAs, and a lack of correlation between myc expression and proliferative activity, max and RB1 mRNAs were detected in most tumours and cell lines." (PMID 8286200, 1994). "One tumor (Ki‐67 15%) showed a stop mutation in RB1 but without the loss of the other allele." (PMID 41416936, 2026). "In melanoma, familial mutations in CDKN2A, RB1, and TERT attenuate senescence, enabling uncontrolled proliferation, whereas ERK5 inhibition triggers senescence via LTBP1-mediated TGF-β1 activation, which suppresses tumor growth and enhances immunotherapy response." (PMID 40781676, 2025). "In these cases, the RB1 gene is not functional, leading to a loss of its tumor suppressor role." (PMID 40317918, 2025). "Alternatively, it is well established that RB1 is involved in multiple tumor‐related pathways through its regulatory role on a number of proteins, such as the E2F family, suggesting that RB1 deficiency may be a relevant event for treatment stratification by targeting activated signaling." (PMID 40904703, 2025). "Similarly, RB1 expression is inconsistent, with about half of the cases showing loss of expression, without a clear correlation to tumor location." (PMID 41246635, 2025). "Importantly, PTK2 expression positively correlated with RB1 levels across all tumor types, suggesting a consistent transcriptional relationship that may reflect a broader, tissue-independent mechanism of regulation." (PMID 40832091, 2025). "In this context, loss of CIC or RB1 alone may be sufficient to induce gene expression changes that facilitate tumor growth even without MAPK signaling amplification, especially at early stages of tumorigenesis." (PMID 41219537, 2025).
tumor (continued). "Also, epigenetic modification, through RB1 promoter hypermethylation, might result in phenotypically variable tumor expression resulting in retinocytoma." (PMID 40001157, 2025). "However, the mere loss of RB1 does not seem to be enough to initiate tumor malignancy, as benign retinomas also display loss of both RB1 alleles." (PMID 39000021, 2024). "Furthermore, the lncRNA PVT1 has been shown to regulate RB1 in GC, contributing to tumor growth." (PMID 38279330, 2024). "As enhanced tumor cell proliferation has been associated with long-term survival in HGSC, and loss of RB1 might accelerate proliferation, we evaluated the expression of proliferation markers across the RB1 and BRCA subgroups." (PMID 38837893, 2024). "Moreover, the HPV oncoprotein E7 inhibits RB1, thereby impairing its tumor suppressive function." (PMID 38545846, 2024). "However, the p16‐high class A tumours were not distinguished by low RB1 expression and no mutation (substitution or Indel) was detected using the RNA‐seq data." (PMID 36453028, 2024). "Although we were readily able to establish RB1 knockout lines, all BRCA1 targeted clones were hemizygous for BRCA1 deletion and retained BRCA1 expression, suggesting that engineered homozygous loss of BRCA1 was cell lethal, even in a tumor type in which BRCA1 loss is frequently observed." (PMID 38837893, 2024). "Finally, losses of CDKN2A in these cell lines or CDKN2A/RB1 in these tumors in the H2 group may also contribute to tumor development and modulate drug responses." (PMID 37369741, 2023). "Similarly, we detected a deleterious variant p.(R455*) on the RB1 gene for case 15 that was only present in the AH but not the tumor (VAF = 90%) that also failed QC (nine reads mapped)." (PMID 37239954, 2023). "Tumor type and RB1 context may affect exactly how FOXM1 expression influences CDK4/6 inhibitor efficacy, meriting further investigation, but there is growing evidence that FOXM1 plays a key role in determining tumor cell responsiveness and resistance to CDK4/6 targeting." (PMID 37686402, 2023). "Since several studies have shown that neoplasms harboring RAD50, BRCA and RB1 mutations are susceptible to a group of pharmacological inhibitors of the enzyme poly ADP ribose polymerase (PARP), patients whose tumors present these mutations might benefit from personalized targeted therapy." (PMID 37373240, 2023).
tumor (continued). "Moreover, restoration of RB1 expression was able to restore tumor cells’ sensitivity to CDK4/6i." (PMID 37835528, 2023). "Similarly, the subunits BRG1 and BRM of the SWI/SNF complex can bind to the oncogene RB1 and enhance the expression activity of RB1, thus suppressing the expression of E2F family genes and arresting cell growth in the G1 phase, inhibiting tumour progression." (PMID 36883311, 2023). "Thus both Rb1 and Rbl1 have detectable tumor suppressor activity in the skin." (PMID 35368709, 2022). "Statistically, tumor focality diagnosed at the first visit was significantly dependent on the status of germline RB1 mutation based on mutation detection using Sanger sequencing and MLPA (P < 0.0001, χ2 test); multifocality was associated with germline RB1 mutation." (PMID 36173648, 2022). "Therefore, the abolishment of aberrant chromosomal looping was enough to make sure the restoration of pRB expression, because correct sequences of RB1 exons in non-RB1-mutational tumor cells would not result in inaccurate pRB translation." (PMID 36175480, 2022). "However, when genetic testing is not available, multifocality in RB regardless of tumor laterality is predictive of germline RB1 mutation." (PMID 36173648, 2022). "Given their similarities, we speculate on why RB1 tumor suppressor activity is unique." (PMID 35368709, 2022). "In the case of Rb1, it may act as either a tumor suppressor or as promoting tumor growth." (PMID 35743985, 2022). "This study included two eyes with less advanced disease (Group B and C) and three with an absence of vitreous seeding, yet detectable levels of tumor-derived cfDNA were identified in every diagnostic sample of AH based either on the identification of SCNAs, pathogenic RB1 SNVs, or both." (PMID 33805776, 2021). "A possible explanation for the lack of visible tumor might be RB1 heterozygous mutation or mutation loss in genetically engineered hESCs or its derived organoids." (PMID 33899024, 2021). "Hence, a combination of inhibitors blocking both pathways could lead to a significant tumor growth reduction together with a decrease in proliferation indexes, including RB1 phosphorylation, E2F1, CCND1, and PCNA expression levels, in the NPC PDX model." (PMID 34204797, 2021). "In our study, the cause of some unilateral RB in aged >12 months was related to RB1 gene site mutation, although without family genetic factors, which might lead to tumor after the second hit of RB cells reported in previous reports." (PMID 34336010, 2021). "The tumor cells with loss of Rb1 and lack of the major targets, intrinsic resistance to CDK4/6 inhibitors may occur." (PMID 34123801, 2021). "In addition, RB1 is one of the most prevalent tumor suppressor genes driving metastasis." (PMID 33591981, 2021). "Thus, we hypothesized that the loss of Rb1 would synergize with MYCN overexpression to reshape the N-Myc cistrome and drive tumor progression." (PMID 34099734, 2021).
tumor (continued). "Despite extensive studies of pRb family proteins, a therapeutic approach that specifically targets defects associated with this tumor suppressor is currently not available, underscoring the need for alternative strategies that can identify new targets for cancers with inactivated RB1." (PMID 33591981, 2021). "Moreover, overexpression and lack of RB1 were also found to be associated with tumor progression and metastasis in hepatocellular carcinoma." (PMID 32013999, 2020). "However, the mechanisms behind this rapid evolution of the tumor go far beyond RB1 inactivation." (PMID 32366932, 2020). "As a result, tumour tissue required to identify sporadic RB1 mutation(s) is not always available." (PMID 30745306, 2019). "Similarly, RB1 acts as tumor suppressor by negatively regulating the cell cycle." (PMID 31038669, 2019). "These comprised two truncating pathogenic variants—RB1 R255* and TSC1 R786*, one missense probable damaging variant—VHL tumor suppressor R58W, and four splice variants of unknown significance in ETS2 transcription factor, SGK1 serum/glucocorticoid regulated kinase 1, AXL RTK and MIB1." (PMID 31258848, 2019). "These CNAs included the loss of CFA22 within RB1 (retinoblastoma tumor suppressor) gene in both tumors, and the loss of CFA26 within PTEN (phosphatase and tensin homologue) gene associated with the loss of a region of CFA11, including CDKN2A (cyclin-dependent kinase inhibitor 2A) in the Dog_2 tumor." (PMID 30514258, 2018). "As Rb1-deficient cells show increased genomic instability we suggest that this novel non-canonical action of Rb1 may contribute to the tumour suppressive actions of Rb1." (PMID 28169375, 2017). "In contrast, NGS of the liver metastasis revealed a deletion in chromosome 13q, including BRCA2, RB1 and ERRC5, accounting for the allele containing the germline BRCA2 p.W563* mutation, which was only present in 4% of sequencing reads (in a sample with 90% tumor content)." (PMID 29262651, 2017). "However, for 6 WES positives without tumor DNA diagnostics, a germ line mutation in RB1 was identified that was always consistent with the somatic RB1 mutation detected by WES, again indicating a high true positivity rate." (PMID 27126562, 2016). "For 12/71 (17%) tumor samples, no RB1 mutations or MYCN amplification could be found by WES (WES negatives)." (PMID 27126562, 2016).